RN7SKP54 (RN7SK pseudogene 54)
Gene: Miscellaneous RNA gene on chromosome 7 (101,058,299 to 101,058,567, forward strand). Ensembl gene ENSG00000222636.
Homologues: Orthologues: chimpanzee 7SK (98% identical). Paralogues in human: RN7SKP90 (75% identical), RN7SKP111 (74% identical), RN7SKP255 (74% identical), RN7SKP37 (74% identical), RN7SKP79 (73% identical), 7SK (73% identical), RN7SKP45 (73% identical), RN7SKP72 (73% identical), RN7SKP134 (72% identical), RN7SKP217 (72% identical), RN7SKP176 (72% identical), RN7SKP211 (72% identical), and 283 more.